TREM1 (triggering receptor expressed on myeloid cells 1)
Diseases named in the same sentence as TREM1 in open-access papers (continued):
Sharing a sentence is not in itself a finding about the gene and the disease.
infectious disease (continued). "Based on the literature using viral PAMPs and other infectious disease models, we further discuss how TREM-1 may influence host-virus interactions and viral pathogenesis." (PMID 25505454, 2014). "Previous studies demonstrated that TREM-1 on monocytes/macrophages could amplify the inflammatory effects in infectious diseases, and interaction between TREM-1 and TLR-4 could enhance the TLR-4 signaling pathway activity leading to multiple proinflammatory mediator secretion." (PMID 31885496, 2019). "sTREM-1, a member of the immunoglobulin superfamily, is a soluble TREM-1 that is upregulated when neutrophils are exposed to bacteria, but not during noninfectious inflammatory diseases, which suggests that sTREM-1 may be a specific marker for infectious diseases." (PMID 34513755, 2021). "TREM-1 and TREM-2, the best-characterized receptors so far, play divergent roles in several infectious diseases." (PMID 25347935, 2014). "Although the pathophysiological role of TREM‐1 was first identified during infectious diseases, increasing studies suggested it participated in no‐infectious disorders." (PMID 37170484, 2023). "Triggering receptor expressed on myeloid cells-1 (TREM-1) is a potent amplifier of pro-inflammatory innate immune responses, but its significance in non-infectious diseases remains unclear." (PMID 27762264, 2016).
bacterial infections (27 papers, 2010 to 2025). "Similar to the NF-κB signal, TREM-1 signal activation amplifies the inflammatory response caused by bacterial infection." (PMID 38098038, 2023). "The blocking of TREM1 reduces inflammation and increases survival in animal models of bacterial infections that cause systemic hyperinflammatory syndromes." (PMID 34531365, 2021). "It has been shown that the blockade of TREM1 reduces inflammation and increases survival in animal models of bacterial infections that cause systemic inflammatory syndromes." (PMID 32391286, 2020). "Our findings indicate lower levels of TREM1 in the Severe CF group, leading to the downregulation of immunity-related genes, may account for increased susceptibility to bacterial infection in severe CF." (PMID 31118097, 2019). "Studies indicate that bacterial infections in neonates trigger TREM-1 activation in leukocytes, leading to an exaggerated secretion of inflammatory cytokines and sTREM-1." (PMID 41226426, 2025). "Evidence suggests that besides CD11c, TREM1 is also a critical receptor in regulating immune responses during the early stages of bacterial infection." (PMID 38694515, 2024). "The immuno-receptor Triggering Expressed on Myeloid cells-1 (TREM-1) is activated during bacterial infectious diseases, where it amplifies the inflammatory response." (PMID 37574520, 2023). "Soluble triggering receptor expressed on myeloid cells 1 (sTREM-1) is upregulated during bacterial infections." (PMID 35047991, 2021). "TREM‐1 is upregulated on neutrophils and monocytes during bacterial infection and, when ligated, acts synergistically with LPS to amplify the pro‐inflammatory response." (PMID 33210468, 2020). "Triggering receptor expressed on myeloid cells 1 (TREM-1), a member of the immunoglobulin superfamily, has been defined as a modifier of local and systemic inflammation, especially in response to bacterial infections." (PMID 31581596, 2019). "TREM1 upregulation was also noted to correlate with the severity of bacterial infection via enhancing NF-κB pathway." (PMID 31781116, 2019). "Bacterial infection can upregulate the membrane-bound and soluble forms of TREM-1, which in turn amplifies inflammation." (PMID 31581596, 2019). "Studies have demonstrated reduced inflammatory responses and mortality rates of animals with bacterial infection due to the blocking of TREM‐1 expression." (PMID 31365951, 2019). "With the emphasis of TREM-1 studies mainly in bacterial infection models, the role of TREM-1 in the regulation of type I IFNs has not been investigated so far." (PMID 25505454, 2014). "The triggering receptor expressed on myeloid cells-1 (TREM-1) is known to be expressed during bacterial infections." (PMID 21496225, 2011). "The results of the present study indicate that TREM-1 can be used as marker of bacterial infection in patients with lung infiltrates." (PMID 20920231, 2010). "TREM-1 myeloid expression and sTREM-1 are reliable markers of bacterial infection among patients with pulmonary infiltrates; sTREM-1 is a predictor of final outcome." (PMID 20920231, 2010). "In bacterial infections, lipopolysaccharide from bacteria induces TREM-1 expression in neutrophils." (PMID 29201022, 2017). "TREM-1 is expressed on neutrophils and macrophages and is up-regulated during bacterial infections." (PMID 27703202, 2016). "Previous studies have demonstrated that the blocking of TREM-1 signaling is associated with a reduction of inflammatory mediators such as IL-1, TNF-α, Monocyte chemoattractant protein 1 (MCP-1) and interferon (IFN)-γ and prolonged survival in mice with bacterial infection." (PMID 30832396, 2019). "The aim of the present study was to define whether expression of TREM-1 on cell membranes of neutrophils (nTREM-1), of monocytes (mTREM-1) and serum sTREM-1 may help in the diagnosis of acute bacterial infections for patients admitted with a new pulmonary infiltrate or pleural effusion." (PMID 20920231, 2010).
bacterial infections (continued). "The transmembrane glycoprotein TREM1, which is found in monocytes, macrophages and neutrophils, is also heavily involved in TLR4 signaling, i.e., it promotes inflammation in response to bacterial infection." (PMID 32325790, 2020). "Studies have demonstrated that TREM-1 expression is significantly upregulated in neutrophils and monocytes from patients with bacterial infections, while its expression remains low in non-infectious inflammatory conditions." (PMID 41226426, 2025). "TREM-1 amplifies TLR-responses and therefore might dangerously enhance the inflammatory response to bacterial infection." (PMID 27253382, 2016).
cardiovascular disease (9 papers, 2016 to 2026). "TREM1 is a promising target for cardiovascular diseases because several TREM1 inhibitors attenuate the formation of atherosclerotic plaques and improve cardiac function after MI in the experimental models." (PMID 38333413, 2024). "However, the significance of TREM1 for guiding clinical diagnosis and treatment of cardiovascular disease still requires further study." (PMID 34221733, 2021). "Therefore, the potential significance of TREM-1 for human cardiovascular disease clearly merits more attention." (PMID 27762264, 2016). "Although most studies about TREM1 all focused on inflammatory diseases such as IBD, we cannot ignore its role in cardiovascular disease due to emerging immune mechanisms in MI." (PMID 34221733, 2021). "However, recently, TREM-1 has been verified to regulate noninfectious cardiovascular disease." (PMID 35637975, 2022).
central nervous system diseases (5 papers, 2022 to 2025). "Soluble Trem1 (sTrem1) in plasma is associated with the development of central nervous system disorders." (PMID 36068612, 2022). "Whether eCIRP causes inflammation through activation of TREM-1 in CNS disorders is an important question for future research." (PMID 36273145, 2022). "Our findings align with observed proinflammatory properties attributed to TREM1 in other central nervous system disorders." (PMID 40011963, 2025). "The nerve injury and toxic effects of CaSR and TREM-1 have been demonstrated in other central nervous system diseases, but little research has been conducted on EBI after SAH." (PMID 36561497, 2022). "Further investigation is warranted to determine whether CIRP mediates inflammatory responses through activation of TREM1 in central nervous system diseases." (PMID 40011963, 2025). "TREM1 has been extensively investigated in infectious and non-infectious diseases, as well as central nervous system disorders, due to its ability to enhance inflammatory/immune responses." (PMID 40011963, 2025).
inflammation (5 papers, 2017 to 2025). Aberrant reaction of the microcirculation characterized by movement of fluid and leukocytes from the blood into extravascular tissues. "Overall, these data suggest that resolution of acute brain inflammation is associated with induction and/or restoration of “homeostatic” microglial signature genes and a transition in the balance of amplifying and modulatory immune signaling via immunoreceptors such as TREM1 and TREM2." (PMID 31156629, 2019). "The enhanced inflammatory response in macrophages has been indicated as a mechanism by which TREM-1 signaling contributes to lung injury; therefore, inhibition of TREM-1 is a potential therapeutic strategy for neutrophil lung inflammation and ARDS." (PMID 34960790, 2021). "We also observed similar divergent Trem1 and Trem2 responses in vivo in response to acute brain inflammation and acute cerebral ischaemia." (PMID 28303091, 2017). "In animal models of LPS-induced ALI, TREM-1 blockade ablates neutrophilic lung inflammation." (PMID 41404075, 2025).
kidney disease (5 papers, 2013 to 2023). "Since TREM-1 signals via the co-receptor DAP12 we evaluated the effect of DAP12 deficiency on the extent of U-IRI kidney disease." (PMID 23844229, 2013). "Because TLRs have been implicated as effectors in kidney diseases and TREM-1 has been previously linked to TLR signaling, we investigated TLR-2 and TLR-4 as putative receptors for kidney DAMPs and macrophage activation." (PMID 23844229, 2013). "Moreover, studies have proved that TREM-1 can be used as a diagnostic marker in kidney diseases, including obstructive kidney disease." (PMID 36691481, 2023). "These relationships between TREM-1 and sTREM-1 with kidney diseases might rationalize our results that sTREM-1 may predict the presence or extent of renal involvement of MPA and GPA." (PMID 37886760, 2023). "To our knowledge we are the first to report TREM1 expression in kidney disease." (PMID 24358193, 2013). "We identified Triggering-Receptor-in-Myeloid-cells (TREM)-1, a regulator of TLR signaling, as highly upregulated in kidney inflammatory macrophages and tested the roles of these receptors in macrophage activation and kidney disease." (PMID 23844229, 2013).
hematological malignancies (3 papers, 2010 to 2025). "In hematological malignancies TREM1 expression is elevated in hematopoietic stem cells during oncogenic stress or persistent DNA damage." (PMID 40677705, 2025).
neurological disorders (3 papers, 2022 to 2025). "In this paper, we provide a general overview of the structure, expression and physiological function of TREM-1 signaling and its role in different neurological disorders." (PMID 36273145, 2022).
brain diseases (2 papers, 2021 to 2022). "Additionally, studies have reported Trem1 as an indicator of neuroinflammation across various brain disorders." (PMID 36068612, 2022). "Targeting at the role of TREM1 and TREM2 in brain structure and brain diseases, many investigations have been conducted, and the results showed that the protein expression of TREM1 and TREM2 in the hippocampus and PFC could be altered by age or inflammatory stimulants." (PMID 34789244, 2021).
colorectal (2 papers, 2017 to 2021). "Triggering receptor expressed on myeloid cells-1 (TREM-1) controls the mobilization of inflammatory cells in response to injury and consequently enhances liver damage." (PMID 34135689, 2021).
immune diseases (2 papers, 2019 to 2025). "The regulation of the TREM-1 signaling pathway by LP17 could significantly affect the progression of inflammation and immune diseases." (PMID 31885496, 2019).
iron metabolic disorder (2 papers, 2020 to 2021). "Treatment of S. typhimurium-infected mice with the TREM-1 inhibitor LP17 was advantageous for ameliorating SpvB-mediated hepatic inflammation and, therefore, iron metabolic disorder." (PMID 33475464, 2021).
TREM1 also shares sentences with these, for which no sentence is quoted: acute myocardial infarction (7 papers); fibrosarcoma (6); ulcerative colitis (6); amyloid (4); cervical carcinoma (3); vasculitis (3); aortic aneurysm (2); atopic dermatitis (2); bacterial pneumonia (2); bladder cancer (2); dementia (2); endocervical adenocarcinoma (2); fatty liver disease (2); gastric ulcer (2); head and neck squamous cell carcinoma (2); hepatitis B (2); IgA nephropathy (2); intestinal tumor (2); kidney failure (2); Klebsiella pneumonia (2); Liver abscess (2); myocardial inflammation (2); peripheral artery disease (2); squamous cell carcinoma (2); tuberculosis (2); ZIKV infection (2); Abdominal obesity (1); acne (1); acute myeloid leukemia (1); adenocarcinoma (1).
A further 82 diseases each share a sentence with TREM1 in 1 paper.